CR1 (complement C3b/C4b receptor 1 (Knops blood group))
Diseases named in the same sentence as CR1 in open-access papers (continued):
Sharing a sentence is not in itself a finding about the gene and the disease.
dengue (3 papers, 2023 to 2026). "In the current study, the minor allele rs6691117G appears to confer protection against dengue fever and progression to severe disease, although it has limited impact on plasma CR1 levels." (PMID 37833411, 2023). "At present, the pathogenesis of dengue virus infection remains incompletely understood, particularly the role of CR1 and CR2 proteins, along with CR1 and CR2 polymorphisms, in dengue disease has yet to be investigated." (PMID 37833411, 2023). "In conclusion, this study revealed a reduction in CR2 levels in dengue patients and that the CR1 SNP rs6691117A/G is associated with the dengue severity." (PMID 37833411, 2023). "In conclusion, the current study revealed that the CR1 rs6691117A/G and CR2 rs1048971G/A SNPs are associated with a progression to the severity of dengue fever." (PMID 37833411, 2023). "The levels of CR1 and CR2 were modulated during the clinical course of dengue fever, with the reduction in CR2 levels associated with disease severity and with previous or current DENV infections." (PMID 37833411, 2023). "The current study is the first to show an association between the CR1 rs6691117A/G and CR2 rs1048971G/A SNPs and the progression to severe dengue fever." (PMID 37833411, 2023). "This present study aims to investigate the potential associations of CR1, CR2 polymorphisms, and plasma CR1 and CR2 protein levels with the severity of dengue fever in Vietnamese patients." (PMID 37833411, 2023). "This study investigated the possible association of genetic polymorphisms and plasma levels of CR1 and CR2 with dengue disease." (PMID 37833411, 2023). "We further compared CR1 protein levels in the followed-up dengue patients at different time points, on the day of admission (T0), after 5 days of admission (T1), and after 8 days of admission (T2)." (PMID 37833411, 2023). "In contrast, CR1 protein levels did not exhibit significant differences among different genotypes of CR1 SNP rs6691117 either in healthy individuals or dengue patients, suggesting that CR1 SNP rs6691117 may not contribute to regulating plasma CR1 levels." (PMID 37833411, 2023). "Notably, we observed the highest levels of CR1 in patients with severe dengue compared to other groups." (PMID 37833411, 2023). "The results revealed that CR1 levels were positively correlated with CR2 levels in both healthy individuals and dengue patients (Spearman's rho = 0.41 and 0.27, respectively, P < 0.0001)." (PMID 37833411, 2023). "Further studies are warranted to elucidate the roles of CR1 and CR2 in the immune response against DENV infection and the progression of dengue fever." (PMID 37833411, 2023). "Although this study represents the first attempt to elucidate the involvement of CR1 and CR2 in the progression of dengue fever, several limitations must be acknowledged." (PMID 37833411, 2023). "We analyzed the correlation of the plasma CR1 and CR2 levels with several laboratory parameters in both healthy controls and dengue patients." (PMID 37833411, 2023). "Our results contribute to a deeper understanding of the roles of CR1 and CR2 during the immune response against DENV infection and the pathogenesis of dengue fever." (PMID 37833411, 2023). "Plasma CR1 and CR2 levels were decreased in dengue patients compared to healthy controls (P < 0.0001) and were associated with platelet counts." (PMID 37833411, 2023). "Consequently, further studies are necessary to elucidate the functional roles of CR1 and CR2 in DENV infection and the clinical progression to severe dengue." (PMID 37833411, 2023). "In addition, we also analyzed the correlation between CR1 and CR2 levels in healthy controls and dengue patients." (PMID 37833411, 2023). "Although CR1 and CR2 have been associated with infections with several viruses such as HIV, HBV, and SARS-CoV-217–19, their roles in the immune response to DENV infection and the progression of dengue fever have not been investigated, so far." (PMID 37833411, 2023).
dengue (continued). "However, we could not show the significant influence of CR1 SNP rs6691117A/G on CR1 levels in healthy controls and dengue patients." (PMID 37833411, 2023).
gallbladder cancer (3 papers, 2014 to 2022). "Recently, it has been indicated that CR1 A3650G (His1208Arg) polymorphism plays a critical role in conferring genetic susceptibility to gallbladder cancer in north Indian population." (PMID 24621201, 2014). "Furthermore, it has been indicated that CR1 A3650G (His1208Arg) polymorphism plays a critical role in conferring genetic susceptibility to gallbladder cancer in north Indian population." (PMID 24621201, 2014). "CR-1-31B, an inhibitor of eukaryotic translation initiation factor 4A, has been found to significantly reduce the growth and initiate the apoptosis of gallbladder cancer cells." (PMID 35874676, 2022).
leukemia (3 papers, 2015 to 2020). A malignant (clonal) hematologic disorder, involving hematopoietic stem cells and characterized by the presence of primitive or atypical myeloid or lymphoid cells in the bone marrow and the blood. "In a group of leukemia patients, comprised of patients with acute myeloid leukemia, acute lymphoblastic leukemia and chronic lymphocytic leukemia, soluble CR1 was found in high concentrations, regardless of specific leukemia type." (PMID 33362763, 2020). "The CR1 and Rel groups were compared for several different measures of disease progression including time to 1%huCD45+ (TT1%), time to 25%huCD45+ (TT25%) and time to overt symptoms of leukaemia (time to leukaemia, TTL)." (PMID 32536690, 2020).
lymph node metastasis (3 papers, 2017 to 2022). "In esophageal squamous cell carcinoma, CR-1 expression was associated significantly with depth of invasion, TNM stage and lymph node metastasis." (PMID 31455359, 2019). "The CR‐1 and VEGF levels were closely related to lymph node metastasis and distant metastasis (p < 0.05)." (PMID 35949510, 2022).
autoimmune hemolytic anemia (2 papers, 2012 to 2025). Autoimmune hemolytic anemia (AIHA) is an autoimmune disorder in which various types of auto-antibodies are directed against red blood cells causing their survival to be shortened and resulting in hemolytic anemia. "In patients with autoimmune hemolytic anemia (AIHA) and rheumatic diseases, RBC immunoprotein coating might take the form of immune complexes, since RBCs are known to express receptors for C3b (CR1) and have a key role in the transport and elimination of immune complexes containing IgG and C3b." (PMID 41019035, 2025).
bacterial pneumonia (2 papers, 2006 to 2019). Acute infection of the lung parenchyma caused by bacteria (e.g., Streptococcus pneumoniae, Haemophilus influenzae, Chlamydia pneumoniae, Mycoplasma pneumoniae, and Legionella pneumophila). "In pneumonia, CR1 had significantly higher levels on neutrophils in patients with bacterial pneumonia compared to those with viral pneumonia." (PMID 32010199, 2019). "Our results suggest that the expression of CR1 is higher in classical bacterial pneumonia than in viral pneumonia." (PMID 16433910, 2006). "On a more general level, this suggests that the expression of neutrophil CR1 is higher in classical bacterial pneumonia than in viral pneumonia." (PMID 16433910, 2006). "Our results suggest that the expression of neutrophil CR1 is higher in classical bacterial pneumonia than in viral pneumonia." (PMID 16433910, 2006). "Although the high expression of neutrophil CR1 is suggestive of classical bacterial pneumonia, it is unlikely that any single parameter of inflammation alone could reliably differentiate between bacterial and viral pneumonia." (PMID 16433910, 2006). "The high level of CR1 in aetiologically undefined pneumonia is consistent with this finding, since one can speculate on epidemiological basis that most of these patients probably had bacterial pneumonia." (PMID 16433910, 2006).
cerebral amyloid angiopathy (2 papers, 2015 to 2019). "Further studies suggested that CR1 (rs6656401) is associated with cerebral amyloid angiopathy and vascular amyloid deposition." (PMID 31366155, 2019).
chronic hepatitis (2 papers, 2020 to 2021). An active inflammatory process affecting the liver for more than six months. "Similarly, low E-CR1 and high levels of IC were observed in patients with chronic hepatitis and liver cirrhosis, emphasizing the importance of defective CIC clearance by altered CR1 functions." (PMID 33718121, 2020).
colitis (2 papers, 2020 to 2024). Inflammation of the colon. "However, research using the Myd88-knockout mouse model, the antibiotic-induced colitis model, and the dextran sulfate sodium (DSS)-induced colitis model all led to the same conclusion: CX3 CR1+ dendritic cells show a great ability to migrate to mLNs and present antigens." (PMID 39144142, 2024).
G6PD deficiency (2 papers, 2008 to 2020). An X-linked genetic condition caused by alterations in the gene G6PD that result in moderately to severely decreased activity levels of the enzyme glucose-6-phosphate dehydrogenase. "The frequency of the host polymorphisms α+-thalassaemia, CR1, ABO blood group, SAO and G6PD deficiency were determined in a group of children from Papua New Guinea (PNG)." (PMID 18173836, 2008).
ischemic stroke (2 papers, 2019 to 2021). A stroke disorder caused by obstruction of blood flow to the brain, due to thrombotic (local blood clot formation) or embolic (due to a blood clot or other material traveling from another site) event. "More studies need to be performed in the future to elucidate the function of CR1 in ischemic stroke." (PMID 31011487, 2019). "It was previously shown that the decoration of soluble human CR1 (sCR1) with sialyl Lewis x (sLE x) moieties enhanced the protective effect of sCR1 in a rat model of selectin-dependent lung injury and in a mouse model of ischemic stroke." (PMID 34899752, 2021). "However, in the pathological process of ischemic stroke, the role of CR1 is still unknown." (PMID 31011487, 2019).
kidney inflammation (2 papers, 2012 to 2021). "Moreover, complement receptor genes CR1, ITGAM, ITGAX and ITGB2 showed a significant link between expression and kidney inflammation." (PMID 34326417, 2021).
Onset (2 papers, 2015 to 2021). The age group in which disease manifestations appear. "The notion that dysregulation of the complement system occurs upstream rather than downstream of an inherent neurodegenerative process is supported by the observation that genetic variability in both Clusterin and CR1 is associated to risk of late-onset AD." (PMID 26502875, 2015).
parasitemia (2 papers, 2010 to 2018). "In order to determine whether we were working at excess concentrations of antibodies and sCR1 we measured the invasion inhibition by anti-CR1 antibody and sCR1 under increasing starting parasitemia." (PMID 20585558, 2010).
pneumococcal infection (2 papers, 2010 to 2019). Infections with bacteria of the species streptococcus pneumoniae. "The CR1 gene was reported to be important for host defense against pneumococcal infection in mice." (PMID 32010199, 2019). "Studies have suggested an important role of CR1/2, CR3 and CR4 in host defense against Streptococcus pneumoniae infections." (PMID 20359357, 2010).
pneumonia (2 papers, 2006 to 2019). An acute, acute and chronic, or chronic inflammation focally or diffusely affecting the lung parenchyma, caused by an infection in one or both of the lungs (by bacteria, viruses, fungi, or mycoplasma.). "In addition, deficiency of CR1 was reported in a patient with OM, sinusitis, and pneumonia." (PMID 32010199, 2019). "A significant difference in the expression of monocyte FcγRI was observed between the patients with pneumococcal and influenza A pneumonia, and in the expression of monocyte CR1 between the patients with influenza A and undefined pneumonia." (PMID 16433910, 2006). "The behaviour of CRP was similar to the expression of neutrophil CR1 in that CRP was significantly higher in pneumococcal and aetiologically undefined pneumonia than in influenza A pneumonia." (PMID 16433910, 2006).
prion disease (2 papers, 2010 to 2017). A transmissible disease that is caused by a protein that is able to induce abnormal folding of normal cellular proteins, leading to characteristic spongiform brain changes, which are associated with neuronal loss without an inflammatory response. "To test whether AD susceptibility genes are also quantitative trait genes for prion disease incubation time in mice we analysed Clu, Picalm and Cr1 in our HS mice." (PMID 21151910, 2010). "Although Picalm and Cr1 have not previously been implicated in prion disease there is ample evidence to suggest that clusterin may be involved." (PMID 21151910, 2010).
prostate tumors (2 papers, 2015 to 2024). "To mimic and study the situation of CR-1 overexpression that is found in some prostate tumors and tumor cells, we ectopically overexpressed CR-1 in two widely used PCa cell lines, LNCaP and 22Rv1 both of which possess an epithelial phenotype and extremely low levels of endogenous CR-1." (PMID 25596738, 2015). "We then investigated a possible link between CR-1 and EMT in human primary prostate tumors by examining expression of vimentin, a robust marker of mesenchymally-derived cells or cells undergoing an EMT." (PMID 25596738, 2015). "We observed several prostate tumors that were completely negative for both CR1 and CR3." (PMID 39518018, 2024).
Stroke (2 papers, 2015). Sudden impairment of blood flow to a part of the brain due to occlusion or rupture of an artery to the brain. "Application of CVF, C1-inhibitor, C3-inhibition through soluble CR1 or C3-deletion, as well as immunoglobulin treatment, have all shown protective effects in adult stroke animal models, suggesting that complement-targeted therapy could prove effective in neonatal HI and needs further investigation." (PMID 25729383, 2015).
tauopathy (2 papers, 2023 to 2026). Neurodegenerative disorders involving deposition of abnormal tau protein isoforms (tau proteins) in neurons and glial cells in the brain. "CR1 is one of the most important risk genes for late-onset AD, it plays multiple roles in the onset of AD, such as Aβ clearance, neuroinflammation, and tauopathy." (PMID 37416324, 2023). "CR1, encoding a type-I transmembrane glycoprotein, is one of the most important risk genes for late-onset AD, playing multiple roles in the onset of AD, such as Aβ clearance, neuroinflammation, and tauopathy." (PMID 37416324, 2023).
uveal melanoma (2 papers, 2011 to 2015). A melanoma derived from melanocytes of the uveal tract. "Expression of CR-1 has been recently described in primary uveal melanomas and uveal melanoma cell lines." (PMID 21863025, 2011).
viral pneumonia (2 papers, 2006 to 2019). Inflammation of the lung parenchyma that is caused by a viral infection. "The aim of the present study was to examine, whether the measurement of the expression of complement receptors (CR1 and CR3) and Fcγ-receptors (FcγRI, FcγRII, and FcγRIII) on neutrophils or monocytes would be of value in differentiating between bacterial and viral pneumonia." (PMID 16433910, 2006).
acute lymphoblastic leukemia (1 paper, 2015). Leukemia with an acute onset, characterized by the presence of lymphoblasts in the bone marrow and the peripheral blood. "CR1, a negative regulator of the complement cascade, has been reported to be hypermethylated in acute lymphoblastic leukemia." (PMID 25965583, 2015).
Alpha-thalassemia (1 paper, 2022). Alpha-thalassemia is an inherited hemoglobinopathy characterized by impaired synthesis of alpha-globin chains leading to a variable clinical picture depending on the number of affected alleles. "To control for this, we checked for the presence of highly prevalent RBC polymorphisms in Papua New Guinea (alpha thalassemia, CR1 exon 22 polymorphism, and GYPC exon 3 deletion) in the reRBC samples used in this study." (PMID 36250048, 2022). "Examples are alpha thalassemia, the CR1 exon 22 polymorphism, and the glycophorin C (GYPC) exon 3 deletion (Gerbich negative blood type)." (PMID 36250048, 2022).
Atrophy (1 paper, 2020). Any weakening or degeneration, especially through lack of use. "Young adults who carry the CR1 SNP rs6656401 had reduced grey matter volume in the entorhinal cortex, an area associated with atrophy in AD patients." (PMID 32907542, 2020).
autism (1 paper, 2021). Persistent deficits in social interaction and communication and interaction as well as a markedly restricted repertoire of activity and interest as well as repetitive patterns of behavior. "As Klf7 with a 2q33.3q34 deletion has been found to be a candidate gene for Autism, and the patients with this deletion also have microcephaly feature, it is possible that Ln-CR1 could be also involved." (PMID 33760820, 2021).
benign prostatic hyperplasia (1 paper, 2015). A non-cancerous nodular enlargement of the prostate gland. "Next, CR-1 expression was assessed immunohistochemically in pathological specimens consisting of 239 benign prostatic hyperplasia (BPH), and 211 PCa cases that were treated by surgical intervention." (PMID 25596738, 2015).
Brain atrophy (1 paper, 2010). Partial or complete wasting (loss) of brain tissue that was once present. "For the primary analysis, we used an additive model to assess whether the following late onset AD-associated variants influence brain atrophy and cognitive dysfunction in MS patients: PICALM (rs3851179), CR1 (rs6656401), CLU (rs11136000), PCK1 (rs8192708), and ZNF224 (rs3746319)." (PMID 21152065, 2010).
cardiomyopathy (1 paper, 2018). A disease of the heart muscle or myocardium proper. "In addition, CR1*AGGGTG was significantly associated with cardiomyopathy (p = 0.028, OR 12.1, 95%CI 1.3-113) and with the absence of heart failure (p = 0.037, OR 11.1, 95%CI 1.15-107) in comparison to controls." (PMID 29323238, 2018). "Interestingly, patients with cardiomyopathy had lower CR1 plasma levels than asymptomatic patients, which might indicate either consumption due to increased complement activation or lower production associated with this clinical manifestation." (PMID 29323238, 2018).
cerebral tumors (1 paper, 2019). "CR-1 has been established as a novel biomarker in colon, breast or cerebral tumors due to its significant presence in the plasma of such cancer patients as compared to the normal volunteers." (PMID 31455359, 2019).
CHARGE syndrome (1 paper, 2019). CHARGE syndrome is a multiple congenital anomaly syndrome characterized by the variable combination of multiple anomalies, mainly Coloboma; Choanal atresia/stenosis; Cranial nerve dysfunction; Characteristic ear anomalies (known as the major 4 C's). "Several genes were reported only in syndromic cases; CHD7 (CHARGE syndrome), CR1 (van der Woude syndrome), EFNB1 (craniofrontonasal syndrome), KISS1R (Kallmann syndrome), MID1 (Opitz G/BBB syndrome), REN (van der Woude syndrome), and SOX9 (Pierre-Robin syndrome)." (PMID 31122291, 2019).
clear cell renal cell carcinoma (1 paper, 2019). "The potential role of CR-1 in clear cell renal cell carcinoma (ccRCC) is still not clear." (PMID 31455359, 2019).
Cognitive impairment (1 paper, 2016). Abnormal cognition is characterized by deficits in thinking, reasoning, or remembering. "If clearance of peripheral Aß diminishes Aß in the brain, the so called “peripheral sink model”, a deficiency in such peripheral clearance due to lower density of CR1 on E, could contribute to the association of the S form linked SNPs with cognitive impairment." (PMID 26914463, 2016).